IL4 (interleukin 4)
Diseases named in the same sentence as IL4 in open-access papers (continued):
Sharing a sentence is not in itself a finding about the gene and the disease.
colitis (continued). "Adoptive transfer of HD-DCs suppresses DNBS-induced colitis, with the greatest benefit occurring in those mice showing significant increases in IL-10 and IL-4 production by splenic T cells." (PMID 28094779, 2017). "Compared with normal rats, the levels of many cytokines including IL-6, TNF-α, IL-17, IL-23, IL-1βand IFN-γ were increased, while IL-13, IL-10 and IL-4 were decreased in TNBS-induced colitis rats." (PMID 29113344, 2017). "The transferred HD-DCs required IL-4Rα and the capacity to secrete IL-10 to drive IL-4 and IL-10 production and to suppress colitis in recipient mice." (PMID 28094779, 2017). "Studies also show that mesenteric lymph node cells from STAT6 (−/−) mice with colitis exhibited reduced secretion of IL-4, IL-13, and IFN-γ." (PMID 28752100, 2017). "Correlation analysis revealed a significant relationship between splenocyte IL-4 production and colitis disease activity score, such that those mice treated with HD-DCs that produced more IL-4 had less severe colitis." (PMID 28094779, 2017). "Western Blotting analysis further confirmed that TNF-α was increased but IL-4 was decreased in colitis tissues of Adamts18 KO mice when compared to those of WT control." (PMID 28145888, 2017). "Consistently, blockade of IL-4 cytokine activity by IL-4 antibody administration exhibited a protective effect in oxazolone-induced colitis." (PMID 28316599, 2017). "Adoptive transfer of HD-DCs attenuates the severity of DNBS-induced colitis and this is accompanied by increased production of IL-4 by mitogen-stimulated splenocytes from the recipient mice." (PMID 28094779, 2017). "The plasma levels of IL-17, KC, IL-1a and IL-4 tended to decrease in the colitis mice fed a SD and subjected to voluntary exercise as compared to the non-exercising mice (p < 0.05) but that change was insignificant." (PMID 28425943, 2017). "Reduces T-cell-mediated colitis by reducing IFNr and IL-17 in the spleen, mesenteric lymph nodes, and lamina propria, and increasing IL-4 and IL-10." (PMID 29163443, 2017). "CD8+ T cells cultured in the presence of IL-4 acquire an IL-10-producing phenotype and after adoptive transfer, these cells are capable of amelioration of colitis." (PMID 26908454, 2016). "We found that transfer of Tbx21−/− T cells induced IL-17A-dependent colitis despite increased frequencies of IL-4-expressing cells in the intestine." (PMID 27193261, 2016). "The DSS colitis model has been characterized by increased serum levels of IL-6, IL-17, and TNFα and elevated levels of IL-4, IL-6, IL-10 and IFNγ have been reported in chronic colitis." (PMID 27177331, 2016). "Histological severity of murine colitis peaked on day 1, accompanied by an increase in the expression of Th2 cytokines including IL-4 and IL-13." (PMID 27966619, 2016). "Murine infection with S. mansoni prevents colitis in a macrophage-dependent but IL-4- and IL-13–independent manner, representing another population of suppressive macrophages." (PMID 27101372, 2016). "Then, pValac::dts::IL-4 was inserted into L. lactis MG1363 FnBPA+ in order to evaluate the therapeutic potential of the recombinant strain against TNBS-induced colitis." (PMID 27576902, 2016). "In detail, real-time PCR data from colonic tissues showed very high expression levels of proinflammatory IL-17A and IFN-γ mRNA in the colon of colitis mice, as well as an increase in colonic IL-4 and IL-10 mRNA, albeit to a lesser extent." (PMID 25313594, 2014). "The levels of TNF-α and IFN-γ increased, but IL-6, IL-17A and IL-4 decreased in lamina propria (LP) of colon in immune milk-fed mice with DSS-induced colitis." (PMID 24686517, 2014). "As for expression levels of Th1 and Th2 signature cytokines, the expression of IFN-γ and IL-4 mRNA were significantly upregulated in IL-17KO mice with severe colitis." (PMID 25254662, 2014).
colitis (continued). "The increased level of IL-4 indicated a possible molecular therapeutic mechanism of ERCs on the colitis mice, which is consistent with previous findings that IL-4 has a protective function in intestinal tract of experimental colitis." (PMID 25475342, 2014). "Our results demonstrate that helminth antigen-induced amelioration of experimental colitis is associated with a downregulation of the proinflammatory cytokines IFN-γ and IL-17A and the upregulation of the anti-inflammatory cytokine IL-4 in the colon." (PMID 25313594, 2014). "In contrast, IL-4 and IL-10 transgenic expression prevented colitis histology, i.e., histology of IL-4, IL-10 or their combination-treated colon tissues appeared almost normal, with a low level of infiltrating leukocytes." (PMID 24314293, 2013). "Recent studies indicated that during acute DSS-induced colitis, there was induction in Th1 and Th17 cytokine profiles and that this converted into a Th2-biased (IL-4 and IL-10) inflammatory profile during the chronic stages of colitis." (PMID 21858153, 2011). "We examined the mRNA expression for a representative TH1 cytokine (e.g. interferon [IFN]-γ), a TH1 inducer (e.g. IL-12), a TH2 cytokine (IL-4) and iNOS, which catalyses the generation of NO from L-arginine and plays a major role in colitis." (PMID 19636180, 2009). "Furthermore, colitis studies showed that the transfer of CGRP + IL-4-treated macrophages significantly amplified the anticolitic effect observed versus the transfer of IL-4-treated macrophages alone." (PMID 39716372, 2025). "For instance, human macrophages polarized with interleukin-4 (IL-4) to an anti-inflammatory phenotype have been shown to promote wound repair in human colon-derived epithelial cells and to limit colonic inflammation in experimental colitis." (PMID 39716372, 2025). "For CD4+ IL-4+ Th2 cells, the induction of colitis by DSS and treatment with any cADSCs did not cause consistent and obvious changes." (PMID 39176394, 2024). "This study found that compared with colitis models induced by DSS, expression levels of NO, TNF-α, IL-1β, and IL-6 were remarkably reduced in the peripheral blood and colon tissues of colitis mice pre-treated by B. tequilensis YB-2, while expression levels of IL-10 and IL-4 significantly increased." (PMID 38998101, 2024). "Seven hub genes IL10, IL4, IL6, IFNG, IL1B, TNF and IL17A might be responsible for causing Colitis and Arthritis, except for Rheumatoid Arthritis." (PMID 36989283, 2023). "IL-4 promotes the healing processes accomplished by macrophages and has an alleviating effect upon patients with colitis, in whom it also limits the activation of monocytes and macrophages in order to prevent the secretion of proinflammatory cytokines, such as IL-1β and TNF-α." (PMID 37189566, 2023). "IL-13 and IL-4 can prompt intestinal fibrosis by down-regulating matrix metalloproteinase synthesis in fibroblasts, which has led to collagen accumulation in the intestinal tissue of in vitro and in vivo experimental models of CD and colitis." (PMID 38058517, 2023). "Furthermore, the probiotic formulation including Bifidobacterium and Lactobacillus reduced the severity of experimental colitis by inducing Treg cell population in MLNs, while concurrently increasing IL-2, IL-4, and IL-10 expression." (PMID 37110390, 2023). "Infection by the nematode, T. spiralis, for example, attenuates DNBS-induced colitis by downregulating Th1-type cytokines, while exposure to eggs of the trematode S. mansoni protects mice from TNBS-induced colitis by diminishing IFNγ levels and enhancing IL-4 production." (PMID 37189818, 2023). "All in all, Dioscin has a protective effect on DSS‐triggered colitis and LPS/IL‐4‐triggered RAW264.7 cell injury, which is achieved by restraining the inflammatory response and colonic macrophage infiltration, especially by regulating the polarization of macrophages." (PMID 35524480, 2022).
colitis (continued). "Moreover, SOCS1-deficient mice exhibited dysregulated IL-4 and IFN-γ secretion in a rodent colitis model." (PMID 36558966, 2022). "The involvement of IL-4 has previously been reported in colitis and colorectal cancer." (PMID 35432477, 2022). "In addition, the induction of colitis in mice by DNBS is followed by the downregulation of the expression of anti-inflammatory IL-4." (PMID 35893393, 2022). "Interestingly, we observed a minor increase in the percentage of IL-4-producing CD4+ T cells in the colitis mouse model, which was also reduced slightly by PYY 3–36." (PMID 35443853, 2022). "In addition, the anti-inflammatory cytokine IL-4, IL-10 secreted by Th2 cells showed a distinctive reduction in the serum and colonic tissues of the colitis mice (M−N)." (PMID 35372817, 2022). "Furthermore, the high dose of CYN enhanced the alternative activation of peritoneal macrophages isolated from colitis mice, as shown by the increased expression of IL-4 and Arg1." (PMID 36278202, 2022). "It was found that rats with immature tapeworms demonstrated increased IL-4, IL-13 and IL-10 expression but were not protected against colitis, while mature H. diminuta caused less severe clinical symptoms." (PMID 36558772, 2022). "In our study, the decrease in IL-4+ and IL-10+ cell frequency in colitis mouse IELs was restored by the administration of T. halophilus, demonstrating that inflammation-related cells invading intestinal tissues may be regulated by T. halophilus." (PMID 35741032, 2022). "Considering that IL-4 signaling could be important for the suppression of induced colitis, we observed a lower content of IL-4 in DNBS-injected mice that has been significantly restored by Ulva treatments at both doses of 50 and 100 mg/kg." (PMID 35893393, 2022). "IL-4 is produced by Th2 cells and can suppress pro-inflammatory cytokine and alleviate colitis." (PMID 34249002, 2021). "IL-4 and IL-10 are anti-inflammatory mediators with plenty of protective effects in colitis." (PMID 34090510, 2021). "Additionally, the dextran sodium sulphate (DSS) induced colitis and T cell transfer model also suggest that IL-4 can promote colitis." (PMID 34737752, 2021). "We also measured Il-4 and Il-13 mRNA expression in the colonic tissues of normal and colitis mice." (PMID 33192516, 2020). "However, the roles of IL-4 in DSS-induced colitis model are still controversial because protective roles of IL-4 have been also reported." (PMID 33192516, 2020). "Hence, the smooth muscle cell-specific IL-4Rα-deficient mouse strain provided us with a tool to understand the role of IL-4/IL-13-reponsive smooth muscle cells in oxazolone colitis." (PMID 32410852, 2020). "The administration of sinapic acid increased the serum levels of IL-4 and IL-10 in colitis mice." (PMID 33312339, 2020). "Therefore, the IL-4Rα-expressing cell type responsible for the regulation of IL-4/IL-13 signalling during oxazolone colitis remains to be determined." (PMID 32410852, 2020). "In contrast, IL-4-treated macrophages are able to attenuate oxazolone colitis." (PMID 32410852, 2020). "Here, we provide evidence that IL-4/IL-13 signalling on intestinal epithelial cells or smooth muscle cells is not important in mediating or preventing exacerbated acute oxazolone-induced colitis." (PMID 32410852, 2020). "The administration of IL-4 was able to prevent chemical-induced colitis in mice." (PMID 33312339, 2020). "We measured the gene expression of the pro-inflammatory cytokines nitric oxide synthase 2 (NOS2) and interleukin 1 β (IL-1β), as well as the anti-inflammatory interleukin-4 (IL-4) cytokine, in colonic tissues before and after induction of colitis and during recovery." (PMID 32349250, 2020). "Results from oxazolone colitis might create a rationale for anti-IL-4-therapy as a candidate in the treatment of UC." (PMID 33371444, 2020). "In addition, both 10 mg/kg and 50 mg/kg sinapic acid significantly increased the mRNA levels of IL-4 and IL-10 in the colons of colitis mice." (PMID 33312339, 2020).
colitis (continued). "From the results obtained, it can be hypothesized as Rg3-RGE + PT protects mice from DSS-induced colitis by the IL-4 protective mechanism." (PMID 33182623, 2020). "Expression of IL-4 was markedly decreased in colonic tissues from rats with untreated colitis." (PMID 30894816, 2019). "Furthermore, IL-4 affects intestinal mucus production, pathogen contact with the epithelium and colitis." (PMID 30665337, 2019). "The protective effects of GLP on colitis induced by DSS were associated with an increase in B cells but a decrease in T cells, mainly a decrease in 17A-producing CD4+ T-LPLs, and a decrease in the production of IL-17A and IL-4 in LP." (PMID 29888292, 2018). "Indeed, via cytokine Th2 production (IL-4, IL-5 and IL-13), they counterbalance the hyper reactive Th1 / Th17 response induced in colitis." (PMID 30592734, 2018). "In addition, activated caspase-3 and IL-4 were co-expressed in CD8+ T cells in the colonic mucosa of children with colitis." (PMID 29922282, 2018). "Development of colitis is often associated with chronic inflammation, characterized by inflammatory cellular infiltration and series of cytokines secretion, such as TNF-α, IFN-γ, IL-6, IL-1β, IL-4, and IL-10." (PMID 29538417, 2018). "Thus, the combination of exposure to an extract of H. diminuta and IL-4 generates a regulatory DC that can suppress colitis." (PMID 28094779, 2017). "Furthermore, the importance of IL-4 in DSS-induced colitis model was confirmed by using IL-4 knockout mice." (PMID 28316599, 2017). "Adoptive transfer of DCs treated with HD+IL-4 attenuated DNBS colitis by ~35%, a degree of suppression similar to ~41% observed with HD-DCs as assessed by disease activity score (DNBS = 13.7 ± 0.9, n = 3; HD-DC+DNBS = 8.2 ± 3.1, n = 3; HD+IL-4-DC+DNBS = 9.0 ± 1.0, n = 4; mean ± SEM)." (PMID 28094779, 2017). "Mice infected with Hymenolepis diminuta and treated with the adult worm extract or treated with IL-4/IL-13–differentiated M2 macrophages have significantly reduced pathology in experimentally induced colitis; this protective effect is abrogated when IL-10 or macrophages are depleted." (PMID 27101372, 2016). "The administration of L. lactis MG1363 FnBPA+ (pValac::dts::IL-4) to animals subjected to TNBS-induced colitis led to an increase in IL-4 expression, tending towards the restoration of baseline levels of this cytokine and hence contributing to the recovery of homeostasis." (PMID 27576902, 2016). "By augmenting the VDR function in invariant NKT cells using VD supplementation, IL-4 and IL-13 secretion could be up-regulated and therefore aggravate Th2-mediated colitis." (PMID 27620138, 2016). "Administration of rSjcystatin significantly reduced inflammatory parameters and ameliorated the severity of the TNBS-induced colitis through decreasing IFNγ in three organs and lifting the level of IL-4, IL-13, IL-10, and TGF-β in the colon tissues, with uptrending Tregs in the MLN and LPMC." (PMID 26728323, 2016). "Our results are consistent with other investigations that showed T. spiralis excretory-secretory antigen-stimulated dendritic cells alleviated experimental autoimmune encephalomyelitis or DSS-induced colitis through inducing Treg that increased the secretion of IL-4, IL-10 and TGF-β." (PMID 27809931, 2016). "In a recent study, rIL-33 induced Th2-type cytokines directly via IL-4 and IL-4R in colitis." (PMID 26161006, 2015). "Thus, further investigations are needed to clarify the role of IL-4 and to determine how ERCs exert therapeutic effects on IL-4 in the colitis." (PMID 25475342, 2014). "In our current study, the mechanisms responsible for IL-4 or IL-10 anti-colitis could be due to control of pro-inflammatory cytokine production and immune cells accumulation in gut tissues." (PMID 24314293, 2013).
colitis (continued). "IL-4 and IL-5 expressions were previously quantified in intestinal tissue and correlated with the clinical and histological severity of colitis in UC patients, and IL-13, which was also found to be up-regulated in UC, was linked to an impaired epithelial barrier function in the gut." (PMID 22539101, 2012). "Like IL-4, IL-6 has been demonstrated to induce Th2 differentiation via direct action on Th cells, while it was also required for the development of Th1 immunity in murine tuberculosis, colitis and experimental autoimmune encephalomyelitis." (PMID 20442861, 2010). "Elevated levels of IL-4 were also seen in sash mice singly deficient in mast cells and in TNF-deficient mice that do not develop colitis under these conditions, compared with Il10−/− mice that develop severe colitis." (PMID 20808919, 2010). "In addition, DSS-induced colitis mice treated with TcES showed a significant increase in the production of IL-4 and the chemokine MCP-1 (CCL2), along with increased production of IL-22 and IL-31, both of which are cytokines involved in protecting the epithelial barrier." (PMID 40576745, 2025). "Additionally, inflammation in colitis is exacerbated by IL-4." (PMID 39451595, 2024). "However, promising effects of IL-4/IL-13 dual antagonist were observed on murine colitis models." (PMID 38058517, 2023). "Administration of 25.2 g/kg BW of FBPE decreased the IFN-γ, TNF-α and IL-4 levels, while enhancing the IL-10 level, and significantly inhibited the abnormally decreased IgG (Model: 13.25 mg/mL, HD: 14.06 mg/mL), showing a reversal effect on the Th1/Th2 levels in colitis." (PMID 35564016, 2022). "Our current results indicated that rCsCP or CsCA might down-regulate the inflammatory responses of colitis mice via elevating Treg cells in both the spleens and MLNs, inducing the release of Th2 cytokines (IL-10, IL-4 and IL-13), and restraining the production of IL-1β and IL-2 cytokines in serum." (PMID 36084127, 2022). "Whereas, rCsCP ameliorated the acute colitis might through activating innate immunity, downregulating the expression of pro-inflammatory factors (IL-12, IL-23r and IL-7), and promoting the production of anti-inflammatory factors (IL-10, IL-4 and IL-13)." (PMID 36084127, 2022). "The cell type responsible for the observed mortality is likely to be Flt3L-dependet dendritic cells, since adoptive transfer of PTEN-/- FL-DCs, but not GM-CSF/IL-4 derived DCs, was sufficient to induce mortality and weight loss after colitis induction in WT recipients." (PMID 35514976, 2022). "Rather than rendering the mice vulnerable to C. rodentium, mice treated with M(IL4)s showed enhanced protection against infection and less colonic histopathology that correlated with reduced mRNA expression of IL-22, IL-17 and IFNγ, hallmarks of C. rodentium-colitis." (PMID 34691050, 2021). "Thus, peroxidized lipids may induce colitis through IL-4, which in the case of humans, would correspond to a UC-like Th2-like response." (PMID 32992618, 2020). "The IL-4 treatment started at height of infection and three days of treatment led to that the pathogen was removed from the colonic epithelial surface earlier than in vehicle or Stat6 inhibitor treated mice and this was accompanied by a 30% decrease in colitis." (PMID 30665337, 2019). "However, the mechanism of IL-4 in colitis remains to be defined." (PMID 28316599, 2017). "Therefore, IL-4 plays a crucial in the development of colitis." (PMID 28316599, 2017). "Thus, we had reason to believe that the elevated level of Th2 cells and their specific cytokine IL-4 in the colons of TRAF5 KO mice might play proinflammatory roles during the development of DSS-induced colitis." (PMID 27110068, 2016).